GSDMD (gasdermin D)
Diseases named in the same sentence as GSDMD in open-access papers (continued):
Sharing a sentence is not in itself a finding about the gene and the disease.
endometrial cancer (16 papers, 2020 to 2025). Primary or metastatic malignant neoplasm involving the endometrium (mucous membrane that lines the endometrial cavity). "CHMP4B, which reverses gasdermin D-mediated pyroptosis in endometrial cancer by remodeling cell membranes, was also associated with adverse OS in the TCGA-UCEC dataset when mRNA expression was high." (PMID 38562170, 2024). "Notably, our results revealed that cleaved gasdermin D-high/CHMP4B-low endometrial cancer was significantly associated with endometrioid carcinoma, FIGO grades 1–2, and favorable RFS." (PMID 38562170, 2024). "ERRα overexpression also promotes glycolytic metabolism and regulates pyroptosis via the NOD-like receptor family pyrin domain containing 3/cysteinyl aspartate specific proteinase-1/gasdermin D (NLRP3/caspase-1/GSDMD) pathway in endometrial cancer cells." (PMID 40429182, 2025). "Estrogen-related receptor alpha (ERRα), a central regulator of cellular energy metabolism linked to poor cancer prognosis, enhances glycolytic metabolism and targets the NLRP3/caspase-1/GSDMD pathway to regulate pyroptosis in endometrial cancer." (PMID 40718836, 2025). "In our previous study, CHMP4B and VPS4A mitigate GSDMD-mediated pyroptosis by promoting cell membrane remodeling in endometrial carcinoma." (PMID 40538398, 2025). "A recent study demonstrated that hydrogen inhibited the growth of endometrial cancer through the pyroptosis pathway mediated by ROS/NLRP3/caspase-1/GSDMD, indicating there is a close relationship between pyroptosis and EC." (PMID 35299842, 2022). "We observed similar results in the LPS- and nigericin- or NAC-treated Ishikawa cells, indicating that GSDMD deletion blocked pyroptotic cell death in endometrial cancer cells (P < 0.05)." (PMID 31924176, 2020). "We performed immunohistochemical staining and western immunoblotting analysis to observe expression of NLRP3, caspase-1, and GSDMD in human and xenograft mice endometrial cancer tissue and cell lines." (PMID 31924176, 2020). "We observed overexpression of NLRP3, caspase-1, and GSDMD in human endometrial cancer and cell lines by IHC and western immunoblotting." (PMID 31924176, 2020). "GSDMD shRNA lentivirus was used to transfect endometrial cancer cells to investigate the function of GSDMD protein in pyroptosis." (PMID 31924176, 2020). "According to the TCGA database, GSDMD protein expression was significantly different between endometrial cancer and normal endometrial tissue, and correlated with pathological type, stage and patient weight." (PMID 31924176, 2020). "Our data demonstrated that GSDMD was recruited to the NLRP3 inflammasome after LPS and nigericin priming in endometrial cancer cells, and that GSDMD was required for mediation by the NLRP3 inflammasome of pyroptosis and IL-1β production." (PMID 31924176, 2020). "This study extended our original analysis of the ability of hydrogen to stimulate NLRP3 inflammasome/GSDMD activation in pyroptosis and revealed possible mechanism (s) for improvement of anti-tumor effects in the clinical management of endometrial cancer." (PMID 31924176, 2020). "Pyroptosis belongs to a novel inflammatory programmed cell death pathway, with the possible prognosis of endometrial cancer related to the terminal protein GSDMD." (PMID 31924176, 2020). "Our previously published article confirms that pyroptosis-related protein nucleotide-binding domain (NOD)-like receptor (NLR) family member pyrin-domain-containing protein 3 (NLRP3), caspase-1, and gasdermin D (GSDMD) were overexpressed in endometrial cancer tissue and cells." (PMID 40538398, 2025). "This theoretical perspective offers valuable insights into reconciling the divergent prognostic implications of high cleaved caspase-1 p20, which indicates a worse prognosis, with the more favorable outlook associated with high cleaved gasdermin D and low CHMP4B expressions in endometrial cancer." (PMID 38562170, 2024).
endometrial cancer (continued). "Immunohistochemistry was used to assess the expression of four pyroptosis-associated molecules (NLRP3, cleaved caspase-1 p20, cleaved gasdermin D, and CHMP4B) in 351 patients with endometrial cancer, and their associations with clinical, pathological, and survival outcomes were analyzed." (PMID 38562170, 2024). "Moreover, GSDMD serves as a prognostic marker and potential therapeutic target for endometrial cancer, considering GSDMD related to Wnt signaling and substance metabolism pathways." (PMID 37965452, 2023). "Recent studies have shown that pyroptosis is a characteristic of autoinflammatory and autoimmune diseases; We found pyroptotic phenomena reflected as high expression of NLRP3, caspase-1, GSDMD, and IL-1β in endometrial cancer lesions as identified by IHC analyses." (PMID 31924176, 2020). "Importantly, future research should aim to analyze tumor tissue sections of the xenograft mouse model in HRW and NC group via the Tandem Mass Tag (TMT) method to explore the roles of GSDMD and hydrogen-activated pyroptosis in endometrial cancer." (PMID 31924176, 2020). "Upregulated expression of NLRP3, caspase-1, and GSDMD were detected in endometrial cancer tissues (N = 546) compared with normal endometrium (N = 35) in TCGA database, significantly difference was seen in NLRP3 and GSDMD in sample type and histological types (P < 0.05)." (PMID 31924176, 2020). "Accordingly, our finding triggers an interest in determining whether the activation of GSDMD by H2 in endometrial cancer cells ultimately triggers pyroptosis." (PMID 31924176, 2020). "Additionally, immunohistochemistry (IHC) and protein immunoblotting studies have shown overexpression of NLRP3, caspase-1, and GSDMD in human endometrial cancer tissues and cell lines, with moderate to strong positive staining for these proteins in tumor sections." (PMID 40718836, 2025). "Moreover, GSDMD activation can exert anti-tumor effects on endometrial cancer." (PMID 37371484, 2023). "Studies have reported that pyroptosis-related protein caspase-1, NLRP3 and GSDMD were highly expressed in endometrial cancer tissue, and hydrogen could inhibit the growth of endometrial cancer by inducing GSDMD-mediated pyroptosis through a ROS/NLRP3/caspase-1 pathway." (PMID 34381721, 2021). "Therefore, GSDMD might be the terminal protein that participates in pyroptosis in endometrial cancer." (PMID 31924176, 2020). "The heatmap in endometrial cancer showed that ELANE and GSDMD were upregulated and GPX4 and TIRAP were downregulated." (PMID 34722500, 2021). "Therefore, we hypothesize that GSDMD is the terminal protein in the pyroptotic sequence in endometrial cancer cells, and that GSDMD-mediated IL-1β secretion occurs via the ROS-NLRP3-caspase-1 signaling pathway is induced by activating effector molecular hydrogen." (PMID 31924176, 2020). "We observed over-expression of NLRP3, ASC, pro-caspase-1, caspase-1, and GSDMD in Ishikawa and HEC1A endometrial cancer cell lines in contrast to endometrial epithelial cells." (PMID 31924176, 2020). "Another study assessed the expression of four pyroptosis-related molecules (NLRP3, cleaved caspase-1 p20, cleaved gasdermin D, and CHMP4B) in 351 endometrial cancer patients via immunohistochemistry and analyzed their associations with clinical, pathological, and survival outcomes." (PMID 40718836, 2025). "To investigate the potential interaction between cleaved gasdermin D and CHMP4B, we conducted a comparative analysis between cleaved gasdermin D-high/CHMP4B-low endometrial cancer and cleaved gasdermin D-low/CHMP4B-high endometrial cancer." (PMID 38562170, 2024). "To evaluate the impact of cleaved gasdermin D-mediated pyroptosis unhindered by CHMP4B, we compared survival outcomes between cleaved gasdermin D-low/CHMP4B-high and cleaved gasdermin D-high/CHMP4B-low endometrial cancers." (PMID 38562170, 2024).
endometrial cancer (continued). "Negative or weak expression of GSDMD was observed in 13.33% (2/15) of endometrial carcinoma cases, and 86.67% (13/15) showed moderate-to-strong expression." (PMID 31924176, 2020). "To evaluate the consequences of cleaved gasdermin D-mediated pyroptosis without CHMP4B-mediated membrane repair, we analyzed the clinicopathologic characteristics of cleaved gasdermin D-low/CHMP4B-high and cleaved gasdermin D-high/CHMP4B-low endometrial cancer." (PMID 38562170, 2024).
endotoxemia (16 papers, 2019 to 2025). "In our study, the increase in liver GSDMD activation preceded the increase in circulating HMGB1 levels during endotoxemia, and hepatocyte-specific Gsdmd deficiency decreased the plasma HMGB1 concentration and improved the survival of mice from 10% to 100%." (PMID 39927458, 2025). "In contrast to pyroptosis mediated by GSDMD‐induced release of HMGB1 in macrophages, GSDMD‐deficient mice typically release HMGB1 during endotoxemia." (PMID 38020710, 2023). "Deletion of HMGB1 in hepatocytes or neutralizing HMGB1 with monoclonal antibodies phenocopies caspase-11- or GSDMD-deficiency in endotoxemia and bacterial sepsis." (PMID 33854044, 2021). "Global gasdermin D (Gsdmd) deletion reportedly prevents death caused by endotoxemia." (PMID 39927458, 2025). "Therefore, endothelial GSDMD activation–mediated endothelial pyroptosis is most likely the decisive cause of endotoxemia-induced death, whereas the cytokine storm driven mainly by the myeloid cell line may aggravate the disease." (PMID 39927458, 2025). "However, the role of endothelial GSDMD in endothelial injury and lethality in lipopolysaccharide-induced (LPS-induced) endotoxemia and the underlying regulatory mechanisms are unknown." (PMID 39927458, 2025). "HMGB1 interacts with RAGE and subsequently participates in endothelial GSDMD-mediated vascular injury in endotoxemia." (PMID 39927458, 2025). "Hepatocyte GSDMD regulates endothelial GSDMD-mediated vascular injury in an HMGB1-dependent manner in endotoxemia." (PMID 39927458, 2025). "In endotoxemia, we demonstrated that hepatocyte GSDMD was responsible for regulating the release of HMGB1." (PMID 39927458, 2025). "They documented that during endotoxemia, caspase-11 and gasdermin D (GsdmD) play a role in translocating HMGB1 from the nucleus to the cytoplasm via the calcium-induced phosphorylation of calcium-calmodulin kinase (camkk)β." (PMID 37896221, 2023). "Treatment of 1,2-diol significantly inhibited the cleavage of GSDMD and Caspase-1 in lung tissue in endotoxemia mice." (PMID 35222388, 2022). "Administration of FeTPPS significantly attenuates HMGB1- and caspase-11–mediated GSDMD cleavage, organ damage, and lethality in endotoxemia and bacterial sepsis." (PMID 33854044, 2021). "In this study, we focused on the role of GSDMD in the regulation of HFD-induced systemic endotoxemia." (PMID 34275417, 2021). "HMGB1 release during endotoxemia was caspase-11/GsdmD dependent via an active way in vivo and in vitro." (PMID 32328059, 2020). "Caspase-11 activation and subsequent GSDMD cleavage lead to the release of IL-1α in endotoxemia and bacterial sepsis." (PMID 31492850, 2019). "GSDMD has emerged as a promising therapeutic target for the treatment of LPS-triggered endotoxemia." (PMID 39927458, 2025). "Therefore, this research validates endothelial GSDMD as a viable pharmaceutical target and provides a basis for the development of future therapeutics for endotoxemia and endotoxemia-induced septic lethality." (PMID 39927458, 2025). "Therefore, the results of these in vivo experiments verified that hepatocyte GSDMD mediated HMGB1 release and subsequently regulated endothelial GSDMD-mediated vascular injury in endotoxemia." (PMID 39927458, 2025). "As revealed by western blot, deletion of caspase-11 abolished the GSDMD cleavage in endotoxemia." (PMID 33854044, 2021). "GsdmD is detrimental in lethal endotoxemia but protective in bacterial sepsis." (PMID 31209224, 2019). "Therefore, the inhibition of hepatocyte GSDMD had a greater protective effect on endotoxemia than did hepatocyte-specific Hmgb1 knockout, and other factors that are released may depend on hepatocyte GSDMD activation and have a lethal effect on endotoxemia." (PMID 39927458, 2025). "However, in vivo studies are needed to elucidate whether hepatocytic GSDMD regulates endothelial GSDMD-mediated vascular injury through the release of HMGB1 in endotoxemia." (PMID 39927458, 2025).
endotoxemia (continued). "Bromodomain-containing protein 4 (BRD4) was recently found to play a critical role in endotoxemia colon by regulating NLRP3/caspase-1/GSDMD-mediated pyroptosis, and BRD4 inhibition could prevent endotoxemia-induced colon damage through blocking inflammation-related pyroptosis." (PMID 36505474, 2022). "Recently, a study showed that Ca2+ influx, which was mediated by the GSDMD pore, resulted in phosphatidylserine exposure to peripheral leukocytes and splenocytes, thereby leading to life-threatening disseminated intravascular coagulation and endotoxemia in mice." (PMID 34858408, 2021). "However, in LPS-induced inflammation GsdmD was not protective, with GsdmD-deficient (GsdmD−/−) mice showing improved survival in lethal endotoxemia with reduced inflammatory mediator release from pyroptotic immune cells." (PMID 31209224, 2019). "Collectively, the results of the in vivo experiments suggest that endothelial GSDMD-mediated systemic vascular injury and lethality are dependent on hepatocytic GSDMD-mediated HMGB1 release in endotoxemia." (PMID 39927458, 2025). "Moreover, CD4-positive T lymphocytes and IECs could secrete GSDMD-NT in high-fat diet (HFD)-induced systemic endotoxemia, and GSDMD-NT killed the Proteobacteria phylum via directly interacting with cardiolipin, thereby restraining gut barrier impairment and intestinal inflammation." (PMID 36505474, 2022). "Surprisingly, as opposed to the protective phenotype of GsdmD−/− mice in lethal endotoxemia, we found significantly increased circulating ALT levels at 6 h after HS/R, suggesting increased liver injury in GsdmD−/− compared with WT." (PMID 31209224, 2019). "Importantly, genetic deletion of Caspase-11 or GSDMD prevents DIC and confers substantial protection during lethal endotoxemia and bacterial sepsis." (PMID 33854044, 2021). "Given that (a) endotoxemia stimulates inflammasomes, (b) GSDMD blockade is protective, and (c) HMGB1 is released during endotoxemia, several groups have drawn the conclusion that HMGB1, therefore, is released in vivo by an inflammasome- and GSDMD-dependent mechanism." (PMID 32917873, 2020).
hepatocellular carcinoma (16 papers, 2022 to 2026). A malignant tumor that arises from hepatocytes. "Additionally, IL‐33 has also been identified as being secreted through GSDMD pores in senescent hepatic stellate cells, thereby promoting obesity‐associated hepatocellular carcinoma and following allergen exposure promoting allergic diseases." (PMID 40783818, 2025). "Crucially, by suppressing ATP synthesis, this process also lowered heat shock protein (HSP) expression, thereby inducing GSDMD-dependent pyroptosis in hepatocellular carcinoma cells and subsequent immune activation." (PMID 41328341, 2026). "Zn-LDH@Mg induced Caspase/Gasdermin D (GSDMD)-dependent pyroptosis in hepatoma cells, enhanced by increased Zn2+ uptake amplifying mitochondrial oxidative stress." (PMID 41328341, 2026). "Combined treatment with anti-PD-L1 and GSDMD inhibitors enhances antitumor effects and inhibits metastasis of hepatocellular carcinoma cells." (PMID 38066523, 2023). "Elevated levels of GSDMD expression positively correlated with PD-L1 expression and predicted poor prognosis in patients with hepatocellular carcinoma." (PMID 38066523, 2023). "Further studies revealed that conjugated BAs induced pyroptosis through increasing cleaved-Caspase-1 and cleaved-GSDMD protein expression in human hepatoma PLC/RPF/5-ASBT cells and primary mouse hepatocytes, which was further confirmed by TEM analysis." (PMID 36690641, 2023). "Moreover, galunisertib 35 triggers the pyroptotic pathway in glioblastoma, pancreatic cancer, and hepatocellular carcinoma through caspase-1/GSDMD activation." (PMID 39316325, 2025). "Similarly, in hepatocellular carcinoma, we observed expression of GSDMD in hepatocytes, endothelial cells, fibroblasts and different immune cell subsets." (PMID 39224600, 2024). "In hepatocellular carcinoma (HCC), positive GSDMD expression has been established as a marker of poor prognosis and identified as a critical driver of hepatocarcinogenesis." (PMID 39994107, 2025). "GSDMD activates the cGAS pathway via K+ efflux and promotes PD-L1 expression via the Ca2+/HDACs/STAT1 signaling pathway in human hepatocellular carcinoma." (PMID 38066523, 2023). "In HepG2 cells, a model of liver carcinoma, when ER stress is stimulated, the ER stress sensor inositol‐requiring enzyme 1α (IRE‐1α) has been identified as the ER‐derived modulator of pyroptosis via direct binding and activation of GSDMD." (PMID 40783818, 2025). "Further detection of GSDM proteins expression in hepatoma cells showed that HGS-ETR1/2 can induce the activation of GSDME, but not GSDMD, by cleavage." (PMID 38049405, 2023). "Interestingly, data from flow cytometry by Annexin V-FITC/PI and detection of pyroptosis-related marker Gasdermin D (GSDMD) by Western blot demonstrated that, overexpressing or knocking down WTAP will not affect cell apoptosis and pyroptosis in hepatoma cells." (PMID 39744575, 2025).
Alzheimer disease (15 papers, 2021 to 2026). A progressive, neurodegenerative disease characterized by loss of function and death of nerve cells in several areas of the brain leading to loss of cognitive function such as memory and language. "Moreover, miR-22, down-regulated in Alzheimer's disease, alleviates Alzheimer's disease-associated inflammation by targeting gasdermin D and inhibiting pyroptosis." (PMID 40242037, 2025). "Notably, in the cerebrospinal fluids from patients with Alzheimer’s disease, the levels of GSDMD was remarkably higher than those from healthy controls, implying that GSDMD might be a diagnostic biomarker for Alzheimer’s disease." (PMID 39253076, 2024). "In this study, we explore the role of pyroptosis and GSDMD in Alzheimer’s disease (AD) and tauopathy models, focusing on the TAU-induced neuroinflammatory process and its correlation with synaptic plasticity loss." (PMID 41486173, 2026). "ADSCs overexpressing miR-22 outperform miR-22 alone in inhibiting gasdermin D expression and enhancing cognitive function in Alzheimer's disease mice." (PMID 40242037, 2025). "The previous study by our group has found that miRNA‐22 can inhibit pyroptosis by targeting GSDMD and improve the memory and motor ability of mice with Alzheimer's disease (AD) mice by inhibiting inflammatory response." (PMID 34250722, 2021). "Like Alzheimer’s disease, GSDMD plays a pathological role in Parkinson’s disease." (PMID 39253076, 2024). "Sevoflurane, the frequently used anesthetic, could activate the NLRP3/caspase-1/GSDMD cascade, and increase tau phosphorylation and β‐amyloid deposition, hence promoting the progression of Alzheimer’s disease." (PMID 39253076, 2024). "In Alzheimer's disease (AD), there is an aberrant activation of inflammasomes, molecular platforms that drive inflammation through caspase-1-mediated proteolytic cleavage of proinflammatory cytokines and gasdermin D (GSDMD), the executor of pyroptosis." (PMID 36895045, 2023). "Notably, the function and effect of GSDMD on other pyroptosis-associated diseases require closer study, such as Familial Mediterranean fever (FMF), gout, Alzheimer’s disease (AD), and Ischemic brain injury." (PMID 35774778, 2022). "The excessive production, activation, and release of IL‐1β, IL‐18, and GSDMD have been implicated in the development and progression of numerous autoimmune and inflammatory conditions, including RA, IBD, Parkinson's disease (PD), Alzheimer's disease (AD), and MS." (PMID 40686254, 2025). "Therefore, GSDMD is a novel therapeutic target for Alzheimer’s disease." (PMID 37921870, 2023).